PRL (prolactin)
Diseases named in the same sentence as PRL in open-access papers (continued):
Sharing a sentence is not in itself a finding about the gene and the disease.
pituitary adenomas (continued). "Hence, when the PRL level increases due to pituitary adenomas, or the ovarian function decreases due to substantial ovarian lesions, patients need surgical resection of the lesions and postoperative adjuvant therapy with drugs." (PMID 36743954, 2023). "Interestingly, in contrast to the secretion of gonadotropins, these pituitary adenomas are devoid of in vivo hormonal secretion despite the possibility of presence of hormones including GH, PRL TSH or ACTH determined immunohistochemically." (PMID 38203605, 2023). "The MET level was increased in prolactin-releasing human pituitary adenoma; however, its physiological significance is unknown." (PMID 37509632, 2023). "Histological analysis revealed a pituitary adenoma with positive staining for prolactin." (PMID 36835974, 2023). "The Medical Subject Heading (MeSH) terms used in the search process included "tamoxifen", "estrogen receptor modulator", "prolactinoma", "dopamine agonist", "cabergoline", "bromocriptine", "resistant prolactinoma", "prolactin-secreting" and "pituitary adenoma"." (PMID 36950000, 2023). "Functional pituitary adenomas may over-secrete pituitary hormones, such as PRL, GH, ACTH, and rarely LH, FSH, and TSH." (PMID 35954322, 2022). "Prolactin (PRL)-secreting adenomas are the most common type of pituitary adenomas." (PMID 35807204, 2022). "Prolactin (PRL)-secreting tumors, or prolactinomas, are the most common pituitary adenomas." (PMID 36558529, 2022). "We could show that patients with prolactin-producing pituitary adenomas (Group A) were significantly younger, had higher pre-operative prolactin levels, and smaller lesions with lower degree of pituitary stalk deviation." (PMID 36147567, 2022). "Twenty-three out of 102 of these aggressive pituitary adenomas were prolactin-secreting tumors." (PMID 35488355, 2022). "Surgical excision is the first-line treatment for functional (hormone-producing) pituitary adenomas, except for prolactin-producing adenomas; however, complete excision is technically challenging, and many patients require long-term medication after the treatment." (PMID 35954322, 2022). "The first-line treatment in PRL-secreting pituitary adenomas is medical therapy with dopamine agonists (DAs), however, about 10-15% of these neoplasms show resistance to these treatments, despite indications for surgical removal of PRL-secreting pituitary adenomas being reviewed in recent years." (PMID 34322092, 2021). "Prolactinoma is a functional pituitary adenoma that secretes excessive prolactin." (PMID 34814904, 2021). "The rebound of PRL levels (930 μg/L) pushed us to start the association with CAB (4.5 mg/week) + ANA, resulting in a nadir of PRL levels of 23 μg/L and in a further size reduction of the pituitary adenoma." (PMID 34173929, 2021). "Hence, confirmatory prolactinoma diagnosis requires both biomarker measurements, indicating sustained elevation of prolactin and radiographic imaging (MRI), showing pituitary adenoma." (PMID 33946142, 2021). "Prolactin (PRL)-secreting adenomas (PRLomas) are the most common pituitary adenomas." (PMID 34173929, 2021). "Participant E fulfilled the clinical criteria for MEN1 syndrome (multiple endocrine neoplasia type 1), with parathyroid hyperplasia (at 27 years of age), prolactin and GH producing pituitary adenoma, and multiple neuroendocrine tumours in the pancreas, all of them less than one cm." (PMID 34711244, 2021). "Furthermore, the overexpression of miR-182-5p in prolactin-secreting pituitary adenomas tissues has also been documented." (PMID 33692756, 2021). "A 29-year-old man suffering from migraine performed a cerebral MR with the incidental detection of pituitary adenoma (17 × 14x15mm, with bilateral cavernous sinus invasion and PRL 1460 μg/L); he also reported decreased libido and erectile dysfunction for two years." (PMID 34173929, 2021). "DAs represent the first-line treatment for PRL-secreting pituitary adenomas." (PMID 33535394, 2021).
pituitary adenomas (continued). "Since miR-130a-3p was down-regulated in prolactinoma, a pituitary adenoma that produces an excessive amount of PRL, we speculate that miR-130a-3p may be involved in PRL regulation." (PMID 32194503, 2020). "ERα inhibition abolished E2-induced PRLR upregulation and PRL-induced ERα phosphorylation, and fulvestrant, an ERα inhibitor, restored pituitary adenoma cell sensitivity to bromocriptine by activating JNK-MEK/ERK-p38 MAPK signaling and cyclin D1 downregulation." (PMID 33173437, 2020). "Contrarily, thyroid cancer had an increased prevalence in patients with GH-secreting pituitary adenomas (aOR 3.17, 95% CI 1.67–6.02), PRL-secreting pituitary adenomas (aOR 3.66, 95% CI 1.45–9.28), and TSH-secreting pituitary adenomas (aOR 6.28, 95% CI 1.34–29.36)." (PMID 31370339, 2019). "X-LAG, which may occur isolated or associated with FIPA, is characterized by pituitary adenomas or pituitary hyperplasia producing most frequently increased levels of GH, GH releasing hormone (GHRH), and prolactin." (PMID 31365626, 2019). "Therefore, in patients with PRL-secreting pituitary adenomas control of PRL excess by dopamine agonists is mandatory to improve glucose and insulin abnormalities." (PMID 31191454, 2019). "Furthermore, large pituitary adenomas with moderate increase in prolactin levels should prompt prolactin dilutions to avoid "hook effect"." (PMID 29152289, 2017). "Instead, it has been described that other ligands, such as Dll1 and Dll4, were underexpressed in non functioning and prolactin secreting adenomas, and overexpressed in corticotropinomas respectively, pointing to a specific Notch system profile for different pituitary adenomas histotypes." (PMID 28915655, 2017). "First, we asked whether the expression of CDK5 or p35 differs in invasive and noninvasive prolactin pituitary adenomas." (PMID 27438154, 2016). "In addition, our findings showed that CDK5 inhibitors can directly or indirectly block cell migration and invasion in prolactin pituitary adenomas." (PMID 27438154, 2016). "Secondly, pituitary adenoma itself might be the origin of macroprolactin and, lastly, macroprolactin might be synthesized peripherally from breast-derivated PRL." (PMID 27195157, 2016). "The GH3 cell line is rat pituitary adenoma cell which produces GH and prolactin." (PMID 26925153, 2016). "In our study, conducted on 28 patients diagnosed with GH-secreting pituitary adenomas, 9 microadenomas (32.1%) and 19 macroadenomas (67.9%) of which 3 were GH and PRL mixed secreting pituitary adenomas (10.7%) were identified by using Magnetic Resonance Imaging." (PMID 27453753, 2016). "Here we explored the mechanisms of CDK5 signaling in prolactin pituitary adenomas." (PMID 27438154, 2016). "The data suggest that CDK5 might also regulate DA resistance and tumor growth in prolactin pituitary adenomas." (PMID 27438154, 2016). "Ultimately, prolactin-producing pituitary adenoma was diagnosed." (PMID 26228535, 2015). "Hormonal control, determined in the 3 months after surgery, was achieved in 47 (69 %) cases of ACTH-secreting pituitary adenomas, 119 (66 %) cases of GH-secreting pituitary adenomas, 262 (85 %) cases of PRL secreting pituitary adenomas, and 6 (86 %) cases of TSH secreting adenomas." (PMID 25270611, 2015). "The most common of functioning lesions was PRL secreting pituitary adenomas (26.4 %), followed by GH-secreting pituitary adenomas (15.4 %), mixed GH/PRL secreting pituitary adenomas (2.2 %), and ACTH-secreting adenomas (5.8 %), followed by TSH secreting adenomas (0.6 %)." (PMID 25270611, 2015). "However, the size of the patient's pituitary adenoma along with increasing prolactin levels can also suggest a macroprolactinoma." (PMID 25861507, 2015). "Interestingly, HMGA1 overexpression also leads to the development of pituitary adenomas secreting prolactin and GH." (PMID 25136513, 2014).
pituitary adenomas (continued). "Non-negligible number of patients with non-functioning pituitary adenoma presented unexpectedly high concentration of prolactin, fraught with a potential risk of misdiagnosis." (PMID 25142896, 2014). "Prolactin-secreting pituitary adenoma patients took bromocriptine orally after discharge." (PMID 25163653, 2014). "Overexpression of the GH-releasing hormone (GHRH) gene in mice results in hyperplasia of pituitary somatotrophs, lactotrophs, and mammosomatotrophs (cells producing both GH and PRL) by 8 months of age that leads to mixed GH and prolactin secreting pituitary adenomas by 10–24 months of age." (PMID 25136513, 2014). "In conclusion, our case suggests that cabergoline may be effective and safe as a first line monotherapy in patients with giant pituitary adenomas cosecreting prolactin and GH." (PMID 23762662, 2013). "Furthermore, in rat prolactin-secreting pituitary adenoma primary cultures it has been shown that melatonin promotes apoptosis directly inducing mitochondrial damage, supporting the involvement of mitochondrial dysfunction in pituitary apoptotic processes." (PMID 24069394, 2013). "As rhEPO demonstrated no direct effect on MMQ cells in vitro, we further examined whether rhEPO regulate tumor growth of pituitary adenomas in vivo using a nude mouse xenograft model of MMQ prolactin-secreting pituitary adenoma cells." (PMID 22086127, 2012). "Furthermore, most of the genes at the DLK1-MEG3 locus are selectively silenced in clinically nonfunctioning pituitary adenomas, ACTH-secreting pituitary adenomas and PRL-secreting pituitary adenomas." (PMID 22666422, 2012). "Besides the transgenic mouse line TSPY-TAg23 represents a useful tumor mouse model for pituitary adenomas secreting PRL and ACTH." (PMID 24710044, 2010). "Prolactin (PRL)-secreting adenomas are pituitary neuroendocrine tumors (PitNETs, also known as pituitary adeno-mas) derived from lactotroph cells and represent more than 30% of all pituitary adenomas and up to 60% of function-al pituitary adenomas both in women and men." (PMID 40995599, 2025). "Normal thyroid function, prolactin levels, and adrenal function excluded secondary endocrine causes, while normal MRI findings and intact pituitary hormone levels ruled out structural hypothalamic‐pituitary abnormalities (pituitary adenoma, etc.)." (PMID 41019007, 2025). "Notably, the screening for macroprolactin enabled us to define the diagnosis of a gonadotroph pituitary adenoma in a patient with a 2.8 cm macroadenoma and an initial prolactin level of 343 ng/mL who was referred to us with a diagnosis of cabergoline-resistant macroprolactinoma." (PMID 39420933, 2024). "Furthermore, ROC curve analysis (AUC of 0.77) revealed that pre-operative PVR >100 may be of prognostic value for predicting prolactin-producing pituitary adenomas." (PMID 36147567, 2022). "However, although human ACTH, GH or PRL-expressing pituitary adenoma show very high expression of the HH signaling inducer SHH and the HH target gene GLI1, a direct link between Hh signaling (e.g. mutations or pathway overactivation) and tumor formation in the AL has not been confirmed." (PMID 33480359, 2021). "Therefore, to reduce drug-related side-effects, we started CAB + ANA with step reductions in CAB dose to 2 mg/week (-0.5 mg after 6 and 12 months), achieving a further reduction of PRL nadir to 18 μg/L, a shrinkage of the pituitary adenoma (up to 11 × 6x6mm) and a better tolerance of CAB." (PMID 34173929, 2021). "Increased prolactin and enlarged pituitary can suggest false pituitary adenoma, moreover the overlapping clinical symptoms such as growth arrest and weight gain associated with pituitary-suprasellar tumors could be differentiated with other childhood suprasellar tumors, i.e., craniopharyngioma." (PMID 32733376, 2020). "Therefore, KDR phosphorylation at Ser-229 may play a critical role in invasiveness and predicting poor prognosis of prolactin pituitary adenomas." (PMID 27438154, 2016).
pituitary adenomas (continued). "However, In1-40 but not In1-19 peptide was found to be as potent as AG in stimulating PRL-oma cell viability, which is in striking contrast with that observed in other pituitary adenoma subtypes wherein In1-19 was found to be more effective than In1-40 in all endpoints analyzed." (PMID 25737012, 2015). "Furthermore, our data demonstrate that Magmas over-expression inhibits Staurosporine-induced apoptosis by hampering cytochrome c release from mitochondria in rat GH/PRL secreting pituitary adenoma cells, influencing Bax and Bcl2 modulation by pro-apoptotic stimuli." (PMID 24069394, 2013). "Pituitary adenoma mitochondrial dysfunction may be mirrored by the morphological changes reported in pituitary oncocytomas, in GH- and in PRL-secreting pituitary adenomas as well as in non functioning pituitary adenomas, where numerous and ultrastructurally abnormal mitochondria have been described." (PMID 24069394, 2013). "METHODS: The proband, a 17-year-old girl with an invasive prolactin (PRL)-secreting Pituitary Neuroedocrine Tumor (Pit-NET), also known as a pituitary adenoma, underwent germline AIP testing, extended to family members." (PMID 42008033, 2026). "Histopathology confirmed a PIT-1-positive pituitary adenoma, with TSH, GH, and prolactin (PRL) positivity." (PMID 41625237, 2026). "Only a few cases of mixed pituitary adenomas that secrete ACTH and prolactin have been reported, with some being responsive to cabergoline, but none have been described during pregnancy." (PMID 41201503, 2025). "Silent pituitary adenomas immunostain for ACTH and TBX19 (silent corticotroph adenomas), or for PRL, or GH, and POU1F1 (silent lactotroph or somatotroph adenomas, respectively)." (PMID 38612778, 2024). "The main patients' inclusion criteria were: serum prolactin (PRL) level of more than 100 ng/ml, presence of pituitary adenoma (PA) on MRI, histologically approved PA by microscopy." (PMID 38375408, 2024). "She underwent transsphenoidal surgery, with a histological examination of the resection specimen revealing a pituitary adenoma binding adrenocorticotrophic hormone (ACTH), prolactin (PRL), and growth hormone (GH)." (PMID 38571819, 2024). "Hormone assays such as plasma ACTH, serum cortisol, prolactin, GH, follicle-stimulating hormone (FSH), luteinizing hormone (LH), and insulin-like growth factor 1 (IGF-1) values which were done as a part of pituitary adenoma workup were analyzed." (PMID 39677352, 2024). "Functioning pituitary adenomas reported were growth hormone secreting (106 studies), ACTH-secreting (95 studies), prolactin-secreting (80 studies) and TSH-secreting (31 studies)." (PMID 36862265, 2023). "Regarding other investigations, in men with T levels < 5.2 nmol/L and increased prolactin levels or reduced LH and FSH levels, pituitary magnetic resonance imaging (MRI) should be performed to exclude a pituitary adenoma/empty sella." (PMID 38132234, 2023). "This case highlights an unusual PHA case of a rare pituitary adenoma with cosecretion of ACTH, GH, and PRL." (PMID 34321093, 2021). "When patients with recurrent multiple ovarian cysts with simultaneous elevation of E2, PRL, mildly elevated or normal FSH, and decreased LH, a pituitary adenoma is highly suspected." (PMID 34248835, 2021). "Pituitary adenoma is a tumour type known to express DRD2, and the DRD2 agonist bromocriptine is already part of the standard treatment regimen in prolactin-producing adenomas." (PMID 31478179, 2020). "Due to the limitations of the clinical data, in vitro experimentation was conducted to determine the potential effects of estrogen or PRL on their canonical pathways, including ERα, pERα, PRLR and D2R expression in pituitary adenoma cells." (PMID 33173437, 2020). "Three pituitary adenomas [cases 3 (FSH), 5 (null cell), 6 (STH, prolactin)] had <10 GAL-positive stained cells and the remaining five were negative for focal GAL staining." (PMID 32265844, 2020).
pituitary adenomas (continued). "On the other hand, in primary cell cultures established from pituitary adenomas, exogenous SHH increased secretion of GH, prolactin, and ACTH from somatotropinomas, lactotropinomas, and Cushing’s tumors." (PMID 32012988, 2020). "A pathological evaluation showed pituitary adenoma, with extensive expression of GH and ACTH, and rare expression of follicle-stimulating hormone (FSH) and PRL." (PMID 32079542, 2020). "Intriguingly, Tg-Hmga2 mice showed a giant phenotype together with a predominantly abdominal/pelvic lipomatosis, and they developed Natural Killer T cell lymphomas and prolactin (PRL) and GH secreting- pituitary adenomas." (PMID 31487906, 2019). "Contrastingly, thyroid cancer showed an increased prevalence in patients with GH-, PRL-, and TSH-secreting pituitary adenomas." (PMID 31370339, 2019). "Contrastingly, thyroid cancer had higher prevalence rates in patients with GH-, PRL-, and TSH-secreting pituitary adenomas." (PMID 31370339, 2019). "The differential expression patterns of six hPRL variants were significantly different among five subtypes of pituitary adenomas (NF−, FSH+-, LH+-, FSH+/LH+-, and PRL+-adenomas)." (PMID 30210449, 2018). "Papillary-type pituitary adenomas are characterized by an increased expression of EG-VEGF, that is correlated with an increased expression of prolactin." (PMID 28386275, 2017). "The histology results indicated that the lesion was a pituitary adenoma, and most neoplastic cells were strongly immunopositive for TSH and GH, whereas all neoplastic cells were immunonegative for PRL." (PMID 28885368, 2017). "In papillary-type pituitary adenomas, the expression of EG-VEGF correlated with the expression of prolactin." (PMID 28386275, 2017). "In summary, our results illustrated that CDK5-mediated KDR phosphorylation controls prolactin pituitary adenoma progression and KDR pSer-229 serves as a potential prognostic biomarker for both noninvasive and invasive pituitary adenomas." (PMID 27438154, 2016). "TSH-secreting adenomas can co-secrete other hormones including GH, prolactin, and gonadotropins; conversely, co-secretion of TSH from a pituitary adenoma in acromegaly is infrequent." (PMID 25614823, 2015). "Twenty-nine miRNAs were identified to be able to predict pituitary adenoma histotype (ACTH-, GH-, PRL-secreting adenomas, and NFA)." (PMID 25548562, 2014). "Pituitary adenomas co-secreting adrenocorticotrophic hormone (ACTH) and growth hormone (GH) are extremely rare, although GH-secreting adenomas co-secrete prolactin in nearly 30–50% of cases." (PMID 24616766, 2013). "In summary in the present study we show that Magmas protects towards apoptotic stimuli also rat GH/PRL- secreting pituitary adenoma cells, beside mouse ACTH-secreting pituitary adenoma cells." (PMID 24069394, 2013). "We report the first case where pasireotide was used in a patient who had a plurihormonal pituitary adenoma co-secreting ACTH, GH and prolactin." (PMID 24616766, 2013). "Because of the high frequency of pituitary adenomas, especially prolactin-secreting ones among MEN 1 patients, we measured serum prolactin but we found a normal level: PRL=11.7ng/ml (normal ranges: 3-18 ng/ml)." (PMID 20108468, 2008). "The patient developed prolactin levels approaching 100 ng/mL without clinical symptoms or MRI evidence of pituitary adenoma." (PMID 42211780, 2026). "Giant prolactinomas are defined as pituitary adenomas (PAs) ≥ 4 cm with plasma prolactin level > 1000 ng/ml with no other co-secretory component." (PMID 41612354, 2026). "In recent years, potential predictors of DA efficacy in PRL-PitNETs (also known as pituitary adenomas) management have been investigated without reaching definitive indications." (PMID 40995599, 2025). "Clinical, imaging, and laboratory differentiation between non-functioning pituitary adenomas (NFPAs) and prolactinomas can be challenging in clinical practice because of their similar presentation and eventual overlap in prolactin levels." (PMID 40960781, 2025).